IL4 (interleukin 4)
Diseases named in the same sentence as IL4 in open-access papers (continued):
Sharing a sentence is not in itself a finding about the gene and the disease.
Pruritus (continued). "Transgenic mice with epidermis overexpressing IL-4 and IL-13 exhibited AD-like symptoms, including skin lesions and pruritus, and both IL-31 transgenic mice and wild-type mice treated with IL-31 developed hallmark features of AD and scratching behavior." (PMID 36232673, 2022). "Several Th2 cytokines can contribute to pruritus during scabies, including IL-4, IL-13 TSLP, IL-31, and periostin." (PMID 33807098, 2021). "An additional role of IL-4 is a potential increase of pruritus by sensitizing neurons to other stimuli." (PMID 33923629, 2021). "Patient's pruritus ani score, anus drainage and damp score, skin lesion score, skin lesion area score, life quality index score and IL-4 and IgE levels in serum, and overall efficacy of treatment were all significantly enhanced." (PMID 34721653, 2021). "Cytokines that are important for pruritus in AD (e.g., IL-31, IL-4, IL-13, and TSLP) transmit their signals via JAK-1 and JAK-2 into the cells." (PMID 34026782, 2021). "This is underscored by the fact that clinical symptoms and pruritus in AD are significantly improved by the anti-IL-4 receptor α (IL-4Rα) antibody dupilumab, which inhibits both IL-13 and IL-4 signaling." (PMID 33233866, 2020). "A previous study using L. plantarum PMO 08 reported an improvement in pruritus by regulating of pro-inflammatory cytokines such as IL-4 and TNF-a." (PMID 33143293, 2020). "IL-31 directly induces pruritus, while IL-4 and IL-13 enhance itching." (PMID 40109398, 2025). "Additionally, signaling from IL-4 and IL-13 receptors in neurons is crucial for sustaining chronic itch." (PMID 39859462, 2025). "By targeting the interleukin 4 (IL-4)/IL-13 pathway, it rapidly controls pruritus and blistering." (PMID 41466952, 2025). "Furthermore, in mice, an injection with IL-4, IL-13, and a combination of both led directly to acute pruritus." (PMID 39126011, 2024). "Dupilumab may also impact the activity of IL-31, an important driver of pruritus, as IL-4 stimulation upregulates IL-31 receptor A expression and is the central driver of T helper 1 or 2 cell precursor polarization." (PMID 39006917, 2024). "IL-4, IL-5, and IL-31 cytokines are relevant for pruritus and could be targets for therapeutic interventions." (PMID 37874473, 2023). "IL-4, IL-33, and IL-13 as well as neuropeptides (BNP, ET-1) increase the expression of TSLP on keratinocytes, opening the door for additional pathogenic pathways to be associated with pruritus." (PMID 37511610, 2023). "Furthermore, ILC2 and IL4 are cytokines that both induce pruritus and are stimulated via basophils through the action of IL33." (PMID 36983094, 2023). "The oral JAK1 inhibitor upadacitinib might suppress the effects of IL-31 or IL-4/IL-13 and block the communication between nerves and eosinophils, leading to the suppression of pruritus." (PMID 36983203, 2023). "By blocking IL-4 and IL-13 on sensory neurons and inhibiting IL-31 production, it may decrease pruritus in PLCA patients as well." (PMID 38137741, 2023). "Pruritus is mainly stimulated by networked communication between the cutaneous immune system, nervous system, and epidermal keratinocytes and can be alleviated by immunosuppressants, or targeted antibody therapy (e.g., anti IL-4/13, anti-IL13, anti-IL31)." (PMID 37511610, 2023). "However, IL-10 expression was shown to be increased in CSU lesions and a CSU mouse model overexpressing IL-10 exhibited increased pruritus and increased IL-2, IL-4, and IFN-γ expression, driven by JAK/STAT signaling." (PMID 35872776, 2022). "Th-2 profile cytokines, such as IL-4, IL-5 and IL-13, play a significant role in the pathogenesis of the disease by switching the immunoglobulin class to IgE and stimulating afferent neurons via IL-4Rα, thereby promoting pruritus." (PMID 34948183, 2021). "However, other studies have shown that both IL-4 and IL-13 also can directly stimulate pruritus in mice and that the application of combinations of these mediators even accelerated itch induction." (PMID 34026782, 2021).
Pruritus (continued). "Mediators which could be directly involved in the venom-induced pruritus include histamine and tryptase released from mast cells, interleukin-4 and interleukin-13 from Th2 lymphocytes, as well as leukotriene C4." (PMID 35387042, 2021). "Patient's baseline information before therapy and clinical symptoms after therapy were observed and compared, including pruritus ani score, anus drainage and damp score, skin lesion score, skin lesion area score, life quality index score, and IL-2, IL-4, and IgE levels in serum." (PMID 34721653, 2021). "In sum, type-2 immune responses and key-cytokines (IL-2, IL-4, IL-13, IL-31) are critically involved in the chronic phase of pruritus pathophysiology, mediating peripheral sensitization mechanisms and abnormal neuro–immune–epithelial cross-talk in several pruritic conditions." (PMID 33807098, 2021). "In addition, IL-4 and IL-13 together induce the conversion of immunoglobulins to IgE in B cells and stimulation of afferent neurons via the IL-4 receptor subunit-α (IL-4Rα) to promote pruritus." (PMID 39697554, 2024). "Based on the available literature, eosinophils, IgG autoantibodies, IgE autoantibodies, SP and its receptor NK1R, IL-31 and its receptor OSMRb, IL-31RA, IL-13, IL-4, periostin, and basophils may be responsible for pruritus in BP and could be potential therapeutic targets." (PMID 39459488, 2024). "Since novel therapeutic targets, including anti-IL-4/IL-13 and anti-IgE, have successfully been used, immunological pathways are suggested to play an important role in the mechanism of pruritus in AIBD and may be used to target pruritus and overall disease activity in these patients." (PMID 36979421, 2023). "Cytokines IL-4 and IL-13, primarily produced by Th2 cells and ILC2s (Group 2 Innate Lymphoid Cells), directly sensitize TRPA1 on sensory neurons, promoting pruritus." (PMID 41596464, 2026). "In conclusion, the LK5 herbal complex has anti-inflammatory properties that reduce LPS- and IL-4/IL-13-induced inflammation, and has anti-AD effects in animal models of DNCB-induced AD and compound 48/80-induced pruritus." (PMID 38258052, 2023). "Cytokines including IL-31, IL-4, IL-13, and TSLP are crucial for pruritus in AD transmit their signals into the cells via JAK-1 and JAK-2." (PMID 36983094, 2023). "Histamine, IL-33, IL-31, IL-4, IL-13, and thymic stromal lymphopoietin (TSLP) have been suggested to be mediators of pruritus in AD." (PMID 35163297, 2022). "JAK/STAT-mediated production of cytokines including IL-4, IL-13, IL-31, and TSLP inhibits the expression of important skin barrier proteins and triggers pruritus in AD." (PMID 35889539, 2022). "IL-31, IL-4, IL-13, TSLP, and IL-5, as well as other cytokines influence inflammation and pruritus in AD." (PMID 34026782, 2021). "IL-4 and IL-5 as key cytokines in the Th2 axis are consistent with the findings of Mast cells in HS41, as well as the pruritus, which is frequently reported by patients." (PMID 30828428, 2018). "IL-4 and IL-13 directly activate TRPA1+ sensory neurons via IL-4Rα, leading to chronic pruritus." (PMID 41596464, 2026). "Conversely, chronic pruritus frequently involves non-histaminergic mechanisms, driven by cytokines such as interleukin-4 (IL-4), interleukin-13 (IL-13), and particularly interleukin-31 (IL-31)." (PMID 41166019, 2025). "The number of IL‐13 positive cells, but not IL‐4 positive cells, in the dermis correlated with the severity of pruritus in BP." (PMID 36477831, 2023). "Th2 cells produce IL-4 and IL-13 driven by the transcription factor GATA3, which can not only induce macrophage polarization to the M2 phenotype but also induce TGF-β1 and collagen synthesis through the JAK-STAT signaling pathway and induce pruritus." (PMID 37705977, 2023).
Pruritus (continued). "The inhibition of JAK ensures the inhibition of receptors; therefore, the subsequent biological effects, from a greater number of cytokines, are variably involved in the pathogenesis of pruritus, not only IL13 and IL4 but also IL31, IL2, IL8, IL25, IL33, IFNγ and thymic stromal lymphoprotein (TSLP)." (PMID 35890180, 2022). "As IL-13/IL-4 activate JAK1–STAT6, JAK1 inhibitor reduces pruritus mediated by IL-31 or IL-13/IL-4." (PMID 33233866, 2020). "Although IL-13/IL-4 have been reported not to induce acute pruritus, a recent study proved that they act as pruritogens and induce scratching behavior." (PMID 33233866, 2020). "The lack of difference in pruritus intensity between AD subgroups may be due to their secretion of comparable levels of IL-4, IL-22 and IL-31, as well as similar levels of tryptase." (PMID 40869144, 2025). "Therapeutic blocking of the IL-4 and IL-13 receptors with dupilumab in CTCL is thought to reduce the synthesis of IL-31, the neuroimmune ‘‘itch cytokine’’, alleviating cancer-related pruritus by directly affecting neurons, even in cases unrelated to Th2 cell inflammation." (PMID 38398754, 2024). "IL‐13, rather than IL‐4, induces recruitment of eosinophils;66 therefore, IL‐13 is speculated to induce pruritus not only through direct stimulation of sensory nerve fibers but also through eosinophil‐mediated mechanisms." (PMID 36477831, 2023).
Autoimmunity (67 papers, 2009 to 2025). The occurrence of an immune reaction against the organism's own cells or tissues. "Experimental infections with Candida albicans in IL-4 deficient mice led to impaired development of Th1 responses, and a Th1 promoting effect of IL-4 has also been observed in autoimmunity, tumor immunity and contact sensitivity reactions." (PMID 24204259, 2013). "Suppressive effects of iNKT cells in autoimmunity are generally thought to be caused by production of the Th2 cytokines IL4 and IL-13, while their immunostimulatory effects in other tumor systems are typically IFNγ-dependent." (PMID 22880059, 2012). "Although it is unclear whether αζDKO Tfr-cells were impaired in suppressive function, they gained expression of Tfh-associated cytokine Il21 as well as Th2-associated cytokines Il4 and Il13, which might have contributed to the IgG1/IgE-predominant antibodies and autoimmunity in Treg-αζDKO mice." (PMID 39651265, 2025). "During an antigen rechallenge, rapid production of IL-4 occurs, which causes apoptosis of neonatal Th1 cells through the formation of heteroreceptor IL-4Rα/IL-13Rα1, which together with regulatory T cells takes part in the control over peripheral tolerance and restrains autoimmunity in adults." (PMID 36619667, 2022). "However, Th2-type cytokines (such as IL-4, IL-5, IL-10, etc.)can lead to less autoimmunity, susceptible to infections, and also may induce pregnancy-tolerance to fetus, providing protection to pregnancy." (PMID 25563385, 2015). "Th1 and Th17 cells, secreting IFN-γ and IL-17, contribute to the inflammatory response, while Th2 cells, secreting IL-4, and Tregs play a critical role in maintaining immune tolerance and preventing autoimmunity by suppressing excessive immune responses." (PMID 38424613, 2024). "This previously unrecognized attribute positions the IL-4 cytokine in the forefront for fine tuning of T cell selection, adjustment of lymphocyte repertoire diversity, and manifestation of autoimmunity." (PMID 39621313, 2024). "In contrast, the IL-4 response was higher in patients with autoimmunity and/or granulomatous disease." (PMID 37243231, 2023). "IL-4 and IL-10 are the main cytokines that regulate the functions of Th2 and provide beneficial effects against autoimmune disorders." (PMID 37111711, 2023). "We also demonstrate the negative regulatory role of IL-10 in C. jejuni induced autoimmunity and provide IL-4 and Siglec-1 blockade as potential therapeutic interventions against GBS." (PMID 35442154, 2022). "In autoimmunity, blocking IL-4 and depleting CD25+ cells also abrogate the ability of rIL-5 to promote Ts2 cells to reduce immune injury." (PMID 34912327, 2021). "On the other hand, IL-4 is the complicated cytokine whose role varies between anti- and proinflammation in autoimmunity." (PMID 34422219, 2021). "According to a recent review, IL-4 is a complicated cytokine whose role varies between anti- and proinflammation in autoimmunity." (PMID 32824277, 2020). "IL-4, for example, is a well-investigated tolerogenic cytokine that is able to suppress inflammatory responses and organ-specific autoimmunity in both animal models and humans." (PMID 31156531, 2019). "Another study reported that the addition of Gal-3BP induced suppression of IL-4, IL-5, and IL-13, Th2-type cytokines related to autoimmunity." (PMID 31402917, 2019). "IL-4 is an anti-inflammatory immunosuppressive cytokine, which plays an important role in tumorigenesis and autoimmunity." (PMID 29137245, 2017). "The mechanism behind the precise regulation of IL-4 is of interest not only for treatment of autoimmunity but also of allergies and asthma where Th2 cytokines play an important pathogenic role." (PMID 28163705, 2016). "This miRNA is also critical for immunological host-defence responses and autoimmunity, as well as immune cell differentiation and their responses to the external stimuli i.e., IL-4 and INF-γ." (PMID 26734715, 2016).
Autoimmunity (continued). "Increased production of IL-2 promotes immunological tolerance and ameliorates autoimmunity by stimulating T regs growth and survival, while more IL-4 and IL-5 indicates a shift towards a Th2 phenotype, which is immunosuppressive in MS and EAE." (PMID 26140285, 2015). "Further, in LAG-3-deficient mice, mercury elicited higher amounts of IL-6, IL-4 and IFN-γ, cytokines known to play a critical role in mercury-induced autoimmunity." (PMID 25122007, 2014). "Higher frequency of severe hypothyroidism was also observed in patients carrying CC genotype of -590C/T interleukin 4 (IL-4) SNP, leading to a lower production of IL-4, one of the key Th2 cytokines which suppresses cell-mediated autoimmunity." (PMID 22654557, 2011). "Of note, patients with autism have increased inflammatory cytokines IL-21, IL-22, IFN-γ, and IL-4 from T cells, decreased antiinflammatory cytokines TGFβ and IL-10, two functional cytokines produced by Tregs, activated T cells, and/or autoimmunity." (PMID 40155813, 2025). "Additionally, we postulate that these alterations in the IL-4 cytokine level, tied to allergic immune responses, underscore immune disorder and play a role in the etiopathogenesis of autoimmunity, as seen in other studies." (PMID 39941611, 2025). "Regarding CVID and SIgAD patients, association studies suggest that defective IL-4 and IL-21 signaling has been linked to an increased prevalence of non-infectious complications, including autoimmunity." (PMID 37243231, 2023). "Furthermore, elevated IL-4/IL-21 serum levels and increased numbers of IL-4/IL-21 producing T cells were observed in several human autoimmune conditions." (PMID 35911775, 2022). "Interestingly, bullous pemphigoid, another type of autoimmune blistering disease similar to, but distinct from, PV, is also featured by a Th2-predominant autoimmunity, showing significantly increased serum IL-4 and IL-13 as compared with healthy individuals." (PMID 29541411, 2018). "Increment of IL-4 has been demonstrated in autoimmune animal models with ameliorated disease." (PMID 29184551, 2017). "Co-existing Th1 and Th2 cytokine elevations (IFN-γ/TNF-α and IL-4/IL-13, respectively) may indicate pathogenic bystander activation, mirroring patterns observed in autoimmune disorders where nonspecific inflammatory responses enforce the immune dysregulation." (PMID 40806391, 2025). "Therefore, C. jejuni induced autoimmunity is IL-4 and CD4 T cell-dependent." (PMID 35442154, 2022). "Concerning the immune-biological monitoring, the best outcome in patients with lower systemic inflammatory baseline profile (neutrophil counts, NLR, CRP,ESR, LDH/LDHNV, and ENA) and higher baseline levels of IL-4, which may promote occurrence of auto-antibody-driven autoimmunity, was found." (PMID 29755670, 2018). "IL-10 is capable of inhibiting the synthesis of proinflammatory cytokines, while IL-12 is linked to autoimmunity by stimulating the production of interferon-gamma (IFN-γ) and tumor necrosis factor-alpha (TNF-α) from T and natural killer (NK) cells, and by reducing IL-4-mediated suppression of IFN-γ." (PMID 20379374, 2010). "Thus IFN-γ and IL-4 represent endogenous mechanisms for regulating Th17-mediated inflammation, which may play a role in preventing or controlling autoimmunity." (PMID 19852819, 2009). "Another study showed a dependency of accelerated autoimmunity and beta cell destruction on increased IFN-γ, IL-12, and IL-17 and decreased IL-4, IL-6, and IL-13 in pediatric patients with T1D." (PMID 37893217, 2023). "Mice lacking this miRNA developed more severe TH17 responses in murine models of autoimmunity, with increased production of IFN-γ and IL-17 and reduced secretion of IL-4." (PMID 32992819, 2020). "ABCs are generated through the interplay of IL-4, IL-21, and IFN-γ in concert with TLR engagement, and have been shown to play a role in the pathogenesis of lupus-like autoimmunity and anti-viral immunity." (PMID 28953967, 2017).
Autoimmunity (continued). "FOXD1 is involved in autoimmunity through its regulation of IFNγ, IL2, IL4, and NFAT complexes." (PMID 35328504, 2022). "Moreover, the epigenetic mechanism of lupus suggests that the abnormal DNA hypomethylation of T cells results in the excessive expression of methylation-sensitive autoimmunity-related genes such as CD70, ITGAL, selectin-l, IL-4, and IL-13 in lupus." (PMID 33282947, 2020). "IL-4 promotes the differentiation of CD4 T cells toward the Th2 phenotype, and IL-10 and TGF-β are known to exert anti-inflammatory activity and to suppress autoimmunity through mechanisms that include the induction of Treg44." (PMID 28851867, 2017). "For instance, the “Th-like” phenotype of DNT cells has been proposed since these cells can secrete several cytokines, including IL-4, IL-17, IFN-γ, and TNF-α, which may regulate the immune response and/or the inflammation in several disease models, including those related to autoimmunity." (PMID 38255272, 2024). "Combining these data leads to the hypothesis that 1,25(OH)2D3 promotes Th2 differentiation and IL-4 production to assist in suppression of autoimmunity, but only when no sufficient IL-4 is present." (PMID 28163705, 2016).